TLR2 (toll like receptor 2)
Diseases named in the same sentence as TLR2 in open-access papers (continued):
Sharing a sentence is not in itself a finding about the gene and the disease.
Cerebral ischemia (39 papers, 2010 to 2025). Restriction of arterial blood supply to the brain associated with insufficient oxygenation to support the metabolic requirements of the tissue. "The recent another study also reported TLR2-deficient mice to show the enhanced repair after focal brain ischemia with higher levels of Gap43 expression and caspases activity for neural plasticity." (PMID 32264906, 2020). "TLR2 is mainly upregulated in lesion-associated microglia 24–72 h after cerebral ischemia but is also observed in astrocytes and endothelial cells." (PMID 28101118, 2016). "Although the central nervous system is a sterile circumstance and no pathogens such as germs or viruses exist under normal or ischemic condition, it is found that cerebral ischemia causes elevation in the expression of TLR2, TLR4, and TLR9 in neurons." (PMID 23864765, 2013). "TLR2-deficient mice displayed less CNS injury compared with wild-type mice in a model of focal cerebral ischemia." (PMID 21982558, 2011). "TLR2 mRNA was upregulated in the brain of mice during cerebral ischemia and expressed in lesion-associated microglia." (PMID 21982558, 2011). "Compared to WT mice, TLR2/4-deficient mice exhibit lower levels of these inflammatory cytokines, smaller infarct volumes, milder neuroinflammation, and higher neuronal survival rates in the ischemic hemisphere after cerebral ischemia–reperfusion injury." (PMID 39649720, 2024). "Moreover, TLR-2 deficiency caused significant reduction of infarct volume and suppressed inflammatory cytokine expression in infiltrating macrophages after brain ischemia." (PMID 28670282, 2017). "This mechanistic synergy provides a strong rationale for investigating its effects on the TLR-2/NF-κB pathway, a key driver of inflammatory cascades in cerebral ischemia." (PMID 40144659, 2025). "BA was found to inhibit the TLR2/4 signaling pathway during cerebral ischemia, reducing expression of TLR2/4 and NF-κB in rat brain tissue." (PMID 38274789, 2023). "Following brain ischemia in mice, TLR2 mRNA levels in resident microglia rises and TLR2 can binds to endogenous ligands." (PMID 35510663, 2022). "Experimental animal studies have shown that it can protect hippocampus CA1 neurons after cerebral ischemia by downregulating TLR2/4–NFκB signaling and upregulating p38/ERK pathway." (PMID 35008558, 2021). "Despite the well-studied effects of TLR2/4 in brain ischemia and hemorrhagic stroke, the role of sTLRs in these conditions remains a gap in the literature." (PMID 34576137, 2021). "Human PRDX5 has been shown to enhance brain ischemia-reperfusion injury through activation of TLR2- and TLR4-mediated inflammation." (PMID 34943005, 2021). "HMGB1 is a nuclear DNA-binding protein and an important DAMP, which activates TLR2/4 and RAGEs signaling following rapid translocation to the cytoplasm or release from dying cells after cerebral ischemia." (PMID 31547018, 2019). "TLR2 appeared to be neuroprotective in cerebral ischemia/reperfusion injury, by enhancing the activation of protective signaling pathways." (PMID 28293064, 2017). "A recent study identified extracellular Prx5 and Prx6 as major TLR2/TLR4-dependent DAMPs in aseptic inflammation after cerebral ischemia." (PMID 26681963, 2015). "A variety of means have been used to demonstrated the effectiveness of inhibiting the expression of TLR2 and TLR4 and their downstream signaling pathways on protecting brain injury caused by cerebral ischemia and reperfusion." (PMID 23864765, 2013). "By contrast, accumulating experimental evidences suggested that TLR2 and TLR4 play crucial roles in modulating inflammatory response caused by cerebral ischemia and reperfusion via linking to their endogenous ligands, respectively." (PMID 23864765, 2013). "In contrast, in the human brain following cerebral ischemia the low molecular weight hyaluronan form is found and a recent report shows that TLR2 activation by low molecular weight hyaluronan inhibits neurosphere formation in vitro." (PMID 23097717, 2012).
Cerebral ischemia (continued). "It is intriguing that despite that there are several studies demonstrating neuroprotection in TLR2 and TLR4-deficient animals following cerebral ischemia, KO of the gene for the downstream adaptor molecule, MyD88, does not provide protection." (PMID 23097717, 2012). "Cerebral ischemia increases the central expression of both TLR2 and TLR4 that play opposite roles in the modulation of ischemic brain injury." (PMID 23251498, 2012). "Our recent work, using an in vivo imaging approach, revealed that the TLR2 response has a marked chronic component following brain ischemia." (PMID 22873409, 2012). "Early in vitro work suggested that all glial cells expressed TLR2, however, in vivo, TLR2 expression was exclusively in microglia activated with cerebral ischemia, or upon axonal injury due to an entorhinal cortex lesion." (PMID 21845170, 2011). "In addition, the aiPLA2 activity of Prdx6 was associated with the secretion of neurotoxic inflammatory factors and a high expression of Toll-like receptor 2/4 (TLR2/4) in cerebral ischemia/reperfusion injury." (PMID 38671897, 2024). "TLR2 is involved in the sterile inflammation occurring in cerebral ischemia." (PMID 31791382, 2019). "Due to a recent report on the detrimental effects of TLR2-deficiency after experimental ischemia in the long-term, we evaluated if the potential detrimental effects of TLR4-inhibiton occur up to 14d after induction of cerebral ischemia." (PMID 26849209, 2016). "However, one report showed that 24 h after cerebral ischemia-reperfusion injury, the area of cerebral infarction in TLR2-knockout mice was increased." (PMID 25928750, 2015). "Recent studies have shown that, compared with a control group, the number of CD11b-positive cells was significantly reduced, and there was a significant reduction in the neuronal death rate in C57BL mice arterially injected with a TLR2 antibody (clone T 2.5) 45 min after cerebral ischemia." (PMID 25928750, 2015). "Recent studies suggest that Toll-like receptors (TLRs), especially TLR2, may have a key role in the progression of brain damage induced by cerebral ischemia." (PMID 25416145, 2014). "Recent evidence suggests that TLRs, especially TLR2, may play a key role in the evolution of brain damage following cerebral ischemia." (PMID 22873409, 2012). "Moreover, adult TLR2-deficient mice demonstrated reduced brain damage and improved functional outcome after MCAO, though contradictory results have demonstrated a TLR-2 dependent increased brain infarct size after cerebral ischemia/reperfusion injury." (PMID 21573120, 2011). "They confirmed earlier findings that TLR2 is indeed up-regulated in cerebral ischemia." (PMID 20628516, 2010). "Similarly, cerebral ischemia rapidly induces protein aggregation, exacerbating IS pathology, raising the possibility that Tlr2 may act in IS through analogous mechanisms." (PMID 41354822, 2025). "Thus, the iPLA2 activity of Prdx6 may play a critical role in cerebral ischemia/reperfusion injury, which might target TLR2/4 inflammatory cascades." (PMID 28424593, 2017). "Emerging clinical and experimental studies have highlighted the key roles of TLR2 and TLR4 in microglia, which contribute to inflammatory responses occurring after cerebral ischemia-reperfusion injuries." (PMID 28101118, 2016). "Similar to TLR2, TLR4 is also significantly upregulated in microglia and astrocytes 24 h after cerebral ischemia." (PMID 28101118, 2016). "Toll-like receptor 2 (TLR2) and Toll-like receptor 4 (TLR4) are considered to mediate the inflammatory reaction of cerebral ischemia injury, and exercise can inhibit the activity of the Toll-like receptor signaling pathway in the peripheral blood of humans." (PMID 23434667, 2013). "There is a definite conclusion on the basis of current findings that TLR2 and TLR4 exert key influences on the pathological process of cerebral ischemia/reperfusion." (PMID 23864765, 2013).
Cerebral ischemia (continued). "In particular, TLR2 and TLR4 were found to be more important than other TLRs in the pathologic progression of cerebral ischemia and reperfusion." (PMID 23864765, 2013). "In a later study, the same authors used knockout mice to show differential roles for TLR2 and TLR4 in cerebral ischemia." (PMID 20628516, 2010). "CD36-deficient mice display significantly reduced TLR2/1-mediated inflammation following cerebral ischemia, suggesting that CD36 is crucial for TLR2/1 signaling in AD and may contribute to sterile inflammation." (PMID 40429737, 2025). "Additionally, TLR2 and TLR4 act as independent mutants to increase vascular permeability after AIS, aggravating inflammatory injury after cerebral ischemia." (PMID 40520774, 2025). "When TLR2/4 binds to the endogenous ligand HMGB1, it triggers a sequence of signal transduction cascades that result in the production of inflammatory cytokines such TNF-α, IL-1β, and IL-6, which exacerbates cerebral ischemia–reperfusion injury." (PMID 39649720, 2024). "On the other hand, more recent investigation demonstrates that post-ischemia TRPV1 inhibition limited neuronal damage by decreasing toll-like receptor 2 (TLR2) and TLR4, which are usually upregulated after brain ischemia and modulate inflammation and neuronal death." (PMID 37020858, 2023). "Moreover, paeonol can suppress Toll-like receptor 2 (TLR2) and TLR4 signaling pathways and reduce proinflammatory factors in a cerebral ischemia-reperfusion injured rat model." (PMID 32774428, 2020). "The results of the present study indicated that paeonol pretreatment can reduce cerebral infarction volume; neurological deficits; TLR2-, TLR4-, Iba1-, NF-κB-, and IL-1β-immunoreactive cell numbers; and TUNEL-positive cells in cerebral ischemia-reperfusion injured rats." (PMID 28101118, 2016). "Moreover, other means have also been exerted to suppress overexpression of TLR2 and TLR4 during cerebral ischemia/reperfusion." (PMID 23864765, 2013). "Ablation of TLR2, 4 and other components of TLR signaling (HMBG1) in vivo seems to decrease infarct size, attenuate inflammatory responses, and improve neurological behavior in animal models of cerebral ischemia." (PMID 21982558, 2011). "However, studies have demonstrated that TLR2 and TLR4 appear to play opposing roles in cerebral ischemia." (PMID 21982558, 2011). "TLR2 and TLR4 both appear to play critical but opposing roles in cerebral ischemia." (PMID 20628516, 2010). "DCX expression may also increase due to neuroinflammation events; for example, in models of cerebral ischemia in mice, colocalization between the DCX and Toll-like receptor 2 (TLR2) and between this receptor and cells positive for the microglial marker IBA-1, have been described." (PMID 37631975, 2023). "Moreover, neurons express TLR2 and TLR4 1 h after cerebral ischemia-reperfusion injuries." (PMID 28101118, 2016).
liver fibrosis (39 papers, 2013 to 2025). "In this study, we established a liver fibrosis model using TLR2-deficient mice and TLR2-normal mice to investigate the role and regulatory pathways of TLR2 in regulating biliary fibrosis induced by C. sinensis." (PMID 36693049, 2023). "TLR2 deficiency reduced liver lesions and inflammation, alleviated the liver fibrosis induced by C. sinensis." (PMID 36693049, 2023). "This study provides a useful mouse model to study the potential mechanisms of parasite-induced liver fibrosis, and explores the role of TLR2 deficiency in liver fibrosis, providing important reference information for understanding liver fibrosis caused by C. sinensis." (PMID 36693049, 2023). "Mounting evidence has shown that a TLR2 deficiency may protect against CCL4-induced liver fibrosis and that TLR4 can exacerbate cholestatic liver fibrosis." (PMID 29954104, 2018). "The TLR2/MyD88/NF-κB signaling pathway, mediated by TLR2, is crucial for macrophage activation and stellate cell promotion, contributing to liver fibrosis progression." (PMID 39199394, 2024). "For example, HBsAg can stimulate RAW264.7 through the TLR2/MyD88/NF-κB signaling pathway, enhancing the mobility, proliferation, and contraction of HSCs, thereby exacerbating liver fibrosis." (PMID 39199394, 2024). "SEA of Schistosoma is known to signal through TLR2/4 on macrophage and modulates granulomatous inflammation and subsequent liver fibrosis." (PMID 39700261, 2024). "For instance, mouse-derived mmu-miR-92a-2-5 can target TLR2 to inhibit Schistosoma japonicum-induced liver fibrosis and downregulate the expression of TLR2-related cytokines such as IL-4, IFN-γ, and TNF-α during S. japonicum infection in mice." (PMID 37559722, 2023). "Previous study showed that TLR2 deficiency reduces liver inflammation and fibrosis in a mouse model of choline-deficient, L-amino acid-defined (CDAA)-caused liver fibrosis." (PMID 36693049, 2023). "In summary, a new role of TLR2 in aggravating C. sinensis-induced parasitic liver fibrosis was identified." (PMID 36693049, 2023). "Statistical analysis showed that the liver fibrosis grade of C. sinensis-infected TLR2-/- mice was significantly lower than that of C. sinensis-infected WT mice (p<0.001, p<0.001, p<0.001)." (PMID 36693049, 2023). "Bacterial translocation and intestinal inflammation in mice promote hepatic fibrosis though TLR2 signaling pathway in lamina propria mononuclear cells and TNFRI signaling on intestinal epithelial cells." (PMID 36693049, 2023). "Exposure of the in vitro NASH models to elafibranor partially reversed the transcriptional modulations, predicting an inhibition of toll-like receptor (TLR)-2/4/9-mediated inflammatory responses, NFκB-signaling, hepatic fibrosis, and leukocyte migration." (PMID 35269515, 2022). "Knockout of TLR2 has been reported to be able to relieve CCl4-induced hepatic fibrosis in mice by downregulating the expression of profibrotic and proinflammatory genes." (PMID 36313326, 2022). "TLR2 deficiency reduces egg burden and promotes T cell activation, and TLR4 deficiency aggravates schistosome immunopathology and liver fibrosis." (PMID 36389166, 2022). "As shown in the heatmap, inflammatory mediators were expressed significantly, with higher levels in the CCL4-induced liver fibrosis mice than in healthy controls (P value TLR-2 0.02, TLR-4 0.003, and TNF-α 0.03)." (PMID 34549998, 2021). "HBeAg activated macrophages via the TLR-2/NF-κB signal pathway and further exacerbated hepatic fibrosis by facilitating motility, proliferation, and contraction of HSCs with the help of macrophages." (PMID 34649530, 2021). "TLR2 promotes hepatic fibrosis-mediated injured intestinal permeability, leading to increased liver exposure to bacterial products from the gut microflora, which promote liver injury, inflammation, and fibrosis." (PMID 28761060, 2017).
liver fibrosis (continued). "In CHC patients, the expression of HA in serum has been shown to increase in accordance with the progression of liver fibrosis, and HA also works as a ligand for TLR2." (PMID 28067328, 2017). "Time course studies further revealed a strong association (r2 ≥ 0.52) between plasma markers of inflammation (TLR2 activators) and hepatic fibrosis markers (Col1A, Timp1, LoxL2)." (PMID 26761430, 2016). "In CCl4-induced liver fibrosis animal model and ConA challenged mice, curcumin inhibits liver expressions of TLR2, TLR4, and TLR9." (PMID 25954568, 2015). "In the study of the treatment of liver fibrosis, curcumin is effective in preventing liver fibrosis partly because of reducing TLR2, TLR4 and HMGB1 expression by inhibiting pro-inflammatory mediators and HSCs activation." (PMID 25284457, 2014). "BSP can improve liver fibrosis by regulating the TLR2/TLR4-MyD88-NF-κB signaling pathway." (PMID 40626309, 2025). "Additionally, BSP exhibits the ability to alleviate hepatic fibrosis through the TLR2/TLR4-MyD88-NF-κB signaling pathway, ultimately achieving hepatic protection." (PMID 40626309, 2025). "Altogether, these data suggest that Surf4 mediates SAA1 secretion, which may activate HSCs in a paracrine manner via TLR2, thus exacerbating liver fibrosis." (PMID 39105051, 2024). "We wondered whether MST1 is downregulated post schistosome infection because SEA acts through TLR2/4 signaling and is important in Schistosoma egg-induced liver fibrosis." (PMID 39700261, 2024). "TLR2 triggered TGF-β1/Smad2/3 and p38/AKT signaling pathways played crucial roles in activating myofibroblasts and promoting the production of IL-6, which exacerbated liver fibrosis caused by C. sinensis." (PMID 36693049, 2023). "As a result, TLR2 has been considered as the potential target for the treatment of liver fibrosis." (PMID 36693049, 2023). "A new role of TLR2 in aggravating C. sinensis-induced parasitic liver fibrosis was identified." (PMID 36693049, 2023). "We confirmed that TLR2 promoted the process of parasitic liver fibrosis." (PMID 36693049, 2023). "TLR2 is involved in the development of C. sinensis-induced liver fibrosis." (PMID 36693049, 2023). "Moreover, the effects of LWPE on the TLR2/NF-κB signalling pathway in hepatic fibrosis rats also deserve further verification." (PMID 36313326, 2022). "Previous studies have shown that various extracts and ingredients of PE possess anti-inflammatory properties; hence, we speculated that TLR2 may be the key target that mediates the anti-inflammatory effects of LWPE in treating liver fibrosis." (PMID 36313326, 2022). "Post-transcriptional suppression of TLR4 expression by let-7i has been shown to contribute to immune responses to C. parvum infection in cultured human cholangiocytes, and mu-miR-92a-2-5p, which targets TLR2, relieves Schistosoma japonicum-induced liver fibrosis." (PMID 32867835, 2020). "Whether the synergistic regulation of TLR2 and TLR4 is also applicable to the pathogenic process of O. viverrini deserves further investigation in future studies, which may provide more possibilities to unravel liver fibrosis in liver flukes." (PMID 36693049, 2023). "TLR2 signalling pathways induce translocation of NF-κB into the nucleus and eventually modulate transcription of genes, as well as the production of inflammatory cytokines, considered to be the major hepatotoxic mediators that participate in the pathological process of liver fibrosis." (PMID 36313326, 2022). "Among the genes, further analysis disclosed that the gene expression levels of TLR2, Col1a1, Col1a2, Col4a1, Col4a2, and Pdgfr-β were changed during the SCU anti-liver-fibrosis process, and qRT-PCR verified this result." (PMID 40243656, 2025). "On the basis of transcriptomics and network pharmacology findings, genes connected with liver fibrosis and the PI3K/AKT signaling pathway, such as Col1a1, Col1a2, Col4a1, Col4a2, TLR2, and Pdgfr-β, were chosen for qRT-PCR validation." (PMID 40243656, 2025).